ARID1A (AT-rich interaction domain 1A)
Diseases named in the same sentence as ARID1A in open-access papers (continued):
Sharing a sentence is not in itself a finding about the gene and the disease.
endometrial cancer (continued). "ARID1A mutations are also found frequently among women with endometrial cancers, with mutation frequency of 40% in uterine endometrioid adenocarcinoma." (PMID 29093822, 2017). "Arid1a loss has been shown to occur in high-grade endometrial cancers, leading to a series of mutations, which occur following Arid1a downregulation." (PMID 26559525, 2015). "First, we verified that loss of ARID1A increases phosphorylation of AKT at Ser-473 (pAKT-Ser473) as has been described in endometrial cancer cell lines." (PMID 24979463, 2014). "In contrast, the abrogating mutation rate of ARID1A is 36.3% in endometrial cancer and 8.91% in hepatocellular cancer." (PMID 25774356, 2014). "The impact of these co-mutations on phosphorylation of AKT has been studied in endometrial cancers and it was found that tumors with mutated ARID1A were associated with increased AKT phosphorylation and pathway activation." (PMID 24559118, 2014). "Taken together, these studies underscore that concomitant ARID1A/B loss defines a highly aggressive group of undifferentiated endometrial cancers characterized by rapid disease progression and insensitivity to conventional platinum and taxane-based chemotherapy." (PMID 41279405, 2025). "Emerging research suggests that ARID1A mutations may also influence the tumor microenvironment and immune response in endometrial cancers." (PMID 40072110, 2025). "Furthermore, in this study, SNVs in phagocytosis regulators such as PTEN and ARID1A exhibited a significantly higher mutation frequency in endometrial cancer compared to other cancer types." (PMID 40396172, 2025). "Therefore, we investigated the suitability of ARID1A deficiency as a biomarker for predicting response to ICIs in endometrial cancer." (PMID 38893118, 2024). "In endometrial cancer, ARID1A, PTEN, and PIK3CA were commonly mutated across all groups." (PMID 38282550, 2024). "ARID1A (AT-rich interactive domain 1A) is the most frequently mutated gene among all chromatin remodeling genes and is detected in many malignancies, particularly in endometrial cancer (EC)." (PMID 38543097, 2024). "Consistently, endometrial cancers have wild-type ARID1A in the primary tumors, whereas the metastatic subclones carry deleterious mutations, further indicating context-dependent function of ARID1A in primary versus metastatic cancers." (PMID 36980292, 2023). "However, a study that used The Cancer Genome Atlas dataset reported that ARID1A mutation alone was associated with better prognosis in patients with endometrial cancer compared to wt ARIDIA." (PMID 36797358, 2023). "Epistasis experiments show that both the hyperacetylation of select SEs and the greater invasive phenotype in endometrial carcinoma observed upon ARID1A deletion is attenuated with either genetic or pharmacologic inhibition of P300, suggesting it is required in the setting of ARID1A loss." (PMID 37415185, 2023). "In addition, the lower mutation rates of TTN, PTEN, PIK3CA and ARID1A have been identified as possible risk factors in endometrial cancer." (PMID 35893039, 2022). "Hence, in this scenario, DNA‐damaging agents that induce similar types of DNA breaks should exhibit synergy with HDAC6 inhibitors in ARID1A‐mutated tumours, including endometrial cancer." (PMID 35167193, 2022). "In our study, those endometrial cancers with an ARID1A mutation showed elevated levels of TILs and PD-L1 scores, and in contrast, cases with CTNNB1 mutated showed low levels of these two biomarkers, which would support this hypothesis." (PMID 36010253, 2022). "Downregulation of MAPK pathways in ARID1A-deficient endometrial carcinoma has been described previously, but whether this is universal among ARID1A-deficient tumors remains to be determined." (PMID 35852858, 2022).
endometrial cancer (continued). "Loss of function mutations in the tumor suppressor gene ARID1A (AT-rich interactive domain containing protein 1A) leading to a loss of protein expression are a frequent observation in both ovarian and endometrial carcinomas of clear cell and endometroid histology." (PMID 34518240, 2021). "Furthermore, it has recently been shown in endometrial cancer that loss of ARID1A expression leads to an increased phosphorylation of AKT at Ser-473." (PMID 24979463, 2014). "Other peaks, such as ATRX mutations in lower grade glioma or ARID1A mutations in endometrial cancer and stomach adenocarcinoma may represent other points of entry for therapeutic intervention." (PMID 25484917, 2014). "However, poorly differentiated endometrial carcinomas, including high-grade endometrioid carcinomas, may also harbor ARID1A mutations." (PMID 40072110, 2025). "The ARID1A variants identified, including the c.3189_3190delinsC (p.Leu1064fs) and c.5320G>T (p.Glu1774*) mutations, highlight the ongoing relevance of chromatin remodeling genes in endometrial cancer, a finding that has been previously reported but remains an area of active research." (PMID 39296440, 2024). "In endometrial cancer, certain genetic signatures are investigated as alternative biomarkers for ICIs, such as ARID1A alterations, associated with higher TILs, supporting the view that deficient ARID1A might be a potential predictor factor for ICIs efficacy." (PMID 36010253, 2022). "However, the existed loss-of-function ARID1A mutations in these endometrial cancer cells could have disrupted the chromatin conformational regulation on PMP22 and GSC loci." (PMID 34689165, 2021). "Interestingly, HPV-driven cancers had a distinct mutational profile with prominent APOBEC signatures, while HPV negative cancers were predominantly endometrial-like cervical cancers with a mutational profile resembling endometrial cancer (ARID1A, PTEN, and KRAS mutations)." (PMID 34283069, 2021). "ARID1A and OSM protein levels are inverse correlated in patients with endometrial cancer, where elevated OSM levels are associated with poor patient survival." (PMID 41800254, 2026). "We here employed a synthetic lethal drug screen for ARID1A and found that JAK/STAT3 pathway is a therapeutic vulnerability in ARID1A-deficient endometrial cancer." (PMID 41800254, 2026). "Loss-of-function mutations in AT-rich interactive domain-containing protein 1 A (ARID1A), accompanied by reduced protein expression, are common in endometrial carcinoma (EC) and correlate with shorter progression-free survival." (PMID 41957354, 2026). "For example, in endometrial cancers, mutations in CTNNB1 frequently co-occur with mutations in PIK3CA, PTEN, and ARID1A, particularly in high-grade endometrioid carcinomas." (PMID 40072110, 2025). "This inverse relationship of ARID1A and PD-L1 is seen in gallbladder cancer, lung cancer, and endometrial cancer." (PMID 40429787, 2025). "In renal cell carcinoma and endometrial cancer cells, ARID1A knockout increased the proportion of cells in the G2/M phase, showing a loss of proper checkpoint control." (PMID 40429787, 2025). "Further investigation of genomic variations demonstrated high-frequency SNVs and CNVs in key regulators such as PTEN, ARID1A, and UBR4, particularly in endometrial cancer, where PTEN and ARID1A mutations were significantly enriched." (PMID 40396172, 2025). "Multi-omics studies have revealed that inactivating mutations in genes encoding components of this complex, particularly AT-rich interactive domain-containing protein 1A (ARID1A) and SMARCA4, are recurrent events in endometrial cancer." (PMID 40940815, 2025).
endometrial cancer (continued). "This compound shows efficacy in epigenetically dysregulated cancers, such as AT-rich interactive domain-containing protein 1A (ARID1A)-mutant endometrial carcinoma and lymphomas." (PMID 41041285, 2025). "Further studies will be needed to define the consequences of specific ‘doses’ of remaining cBAF abundance in ARID1A-mutant endometrial carcinomas." (PMID 41279405, 2025). "Based on the results of this study, it is too early to consider ARID1A a biomarker for ICIs in endometrial cancer." (PMID 38893118, 2024). "ARID1A, a critical component of the SWI/SNF chromatin remodeling complex, has been frequently implicated in various cancers, including endometrial cancer." (PMID 39296440, 2024). "Alterations of ARID1A were accompanied with mutations in MMR-related genes and associated with higher expression of PD-L1 and better prognosis in patients with endometrial carcinoma." (PMID 38587186, 2024). "AT-rich interactive domain 1A (ARID1A), located on human chromosome 1p35.3, is a frequently mutated gene locus in many tumors, including OCCC, endometrial cancer, ovarian endometrioid cancer, gastric cancer, colorectal cancer and pancreatic cancer." (PMID 36873929, 2023). "As expected, expression of MAPK signaling molecules (B-Raf_pS445, MEK1_pS217_S221, ERK2, p38_pT180, and p90RSK) were negatively correlated with ARID1A expression in the “MDACC endometrial carcinoma” dataset." (PMID 38071325, 2023). "Dysregulation of the phosphatidylinositol 3-kinase (PI3K) pathway, mitogen-activated protein kinase (MAPK) pathway, catenin beta 1 (CTNNB1), or AT-rich interaction domain 1A (ARID1A or BAF250) appears common in endometrial cancer patients." (PMID 35269532, 2022). "The ARID1A loss has been associated with a higher sensitivity to elesclomol (an HSP-90 inhibitor with pro-apoptotic activity), in endometrial cancer cell lines." (PMID 35328145, 2022). "It should also be noted that certain types of endometrial cancers have higher rates of ARID1A alterations: ~40% in uterine endometrioid carcinomas and 20–36% in uterine carcinosarcomas, but they are less frequent in endometrial serous carcinoma." (PMID 36077815, 2022). "The TCGA analysis of endometrial cancers has showed that many of these ancestral genes (PTEN, PIK3CA, KRAS, ARID1A, or CTNNB) are frequently mutated (26–80%) indicating that they are likely drivers of oncogenesis." (PMID 36299398, 2022). "In summary, the findings exposed in this work indicate that the inhibition of HDAC6 activity is a potential therapeutic strategy for patients suffering from ARID1A‐mutant endometrial cancer diagnosed in advanced stages." (PMID 35167193, 2022). "A total of 50 endometrial carcinomas were characterized for ARID1A mutations (using targeted DNA next-generation sequencing—NGS), ARID1A gene expression (using RNAseq and qRT-PCR), and ARID1A protein expression (using immunohistochemistry—IHC)." (PMID 35328145, 2022). "Although our study did not include data on mutations, the POLE mutation has been reportedly observed in approximately 10% of endometrial cancers with ARID1A alteration." (PMID 34257552, 2021). "At the molecular level, type I endometrial cancer is associated with mutations in genes such as PTEN, KRAS, ARID1A, PIK3CA, and CTNNB1 and microsatellite instability (MSI)." (PMID 34565373, 2021).
endometrial cancer (continued). "Significant differences were observed between FIGO stages I-IV clear cell and endometrioid subtypes of ovarian and endometrial cancer according to the protein expression status of ARID1A." (PMID 34257552, 2021). "Immunohistochemical staining to determine the expression of ARID1A and PTEN in endometrial carcinoma revealed a concurrent occurrence of ARID1A and PTEN inactivation." (PMID 34036097, 2021). "Further studies are necessary to elucidate the actual role of SIRT1 in endometrial cancer and its correlation with ARID1A an β-Catenin." (PMID 32388637, 2020). "PTEN, PIK3R1, and ARID1A alterations were significantly more commonly occurred in cases of endometrial cancer than in EIN (p all < 0.05)." (PMID 30886832, 2019). "ARID1A mutations have been increasingly reported upon the emergence of NGS technology especially among various malignancies including endometrial cancer." (PMID 30057548, 2018). "Immunohistochemical studies using phosphatase and tensin homolog (PTEN) and ARID1a on curettage materials can be helpful to exclude concomitant endometrial carcinoma." (PMID 28890426, 2017). "Most molecular studies in endometrial cancer have focused on the most common form, uterine endometrioid carcinoma (UEC), which is primarily driven by PTEN loss and mutations in FGFR2, ARID1A, CTNNB1, PIK3CA, PIK2R1, and KRAS." (PMID 26170901, 2015). "Although MCF7 contains a moderately activating mutation of PIK3CA, depletion of ARID1A by siRNA considerably increased phosphorylation of AKT at Ser-473 in this cell line in endometrial carcinoma cell lines." (PMID 24979463, 2014). "An important observation was that siRNA knockdown of ARID1A in endometrial cancer cell lines per se led to an increased phosphorylation of AKT, indicating a regulation of the PI3K/AKT pathway activity by ARID1A." (PMID 24036443, 2013). "Additionally, the knockout of ARID1A in endometrial cancer cells decreased pro-apoptotic proteins (caspase 7, caspase 9, and p21), leading to increased survival and proliferation of damaged cells." (PMID 40429787, 2025). "ARID1A and ARID1B are paralog subunits that specifically nucleate the assembly of cBAF complexes and are frequently co-mutated in highly aggressive dedifferentiated/undifferentiated endometrial carcinomas (DDEC/UECs)." (PMID 41279405, 2025). "The relationship between ARID1A deficiency and the efficacy of ICIs in endometrial cancer has not yet been analyzed." (PMID 38893118, 2024).
endometrial cancer (continued). "The high frequency and severity of novel VUS, particularly in genes like ARID1A and PTEN, suggest that these variants may play a more critical role in endometrial cancer than currently understood." (PMID 39296440, 2024). "The discovery of new therapeutic strategies against ARID1A may improve the prognosis of endometrial cancer." (PMID 38893118, 2024). "However, as ARID1A was found to be unsuitable for use as a biomarker for deciding on ICI therapy for patients with endometrial carcinoma in this study, it is necessary to reconsider its use in genomic medicine." (PMID 38893118, 2024). "Similarly, homozygous or heterozygous ARID1A loss in the mouse endometrial epithelium, when combined with PIK3CAH1047R mutation, led to the development of endometrial carcinoma." (PMID 38275587, 2023). "Indeed, loss of BAF components, including dual loss of ARID1A and 1B, loss of SMARCB1, and loss of SMARCA4, are found in more than half of dedifferentiated and undifferentiated endometrial carcinoma, in a mutually exclusive manner." (PMID 38275587, 2023). "Interestingly, wild-type ARID1A gene has been reported in an individual with endometrial cancer tissues." (PMID 35783357, 2022). "Intriguingly, in endometrial cancer, ARID1A is a pathogenic gene of MSI rather than a target gene due to its function in the epigenetic silence of the MLH1 gene." (PMID 34671561, 2021). "Consistent with this there is some overlap with ARID1A-driven diseases such as endometrial cancer." (PMID 34731603, 2021). "Moreover, loss of ARID1A is significantly associated with microsatellite instability (MSI), predominantly resulting from sporadic MSI (MLH1 promoter hypermethylation), in endometrial cancer." (PMID 33541386, 2021). "Additionally, we performed 3C and ChIP-qPCR assays in human endometrial cancer cell lines ISK and HEC-1-A, because ARID1A mutations are prevalent in this type of cancer." (PMID 34689165, 2021). "This study investigates the feasibility and the prognostic impact of the novel surrogate TCGA molecular classification of endometrial carcinoma into the clinical setting proposing an immuno-molecular algorithm supplemented with ARID1A and CTNNB1/β-catenin analysis." (PMID 33668727, 2021). "In endometrial carcinomas, the PI3K-AKT pathway is activated by an ARID1A mutation." (PMID 34063990, 2021). "ARID1A mutations were identified in both endometrial cancer subtypes but more commonly seen in the ER negative subtype." (PMID 30057548, 2018). "Recent studies showed inactivation of SWI/SNF complex subunits such as INI1 (SMARCB1), BRG1 (SMARCA4) and ARID1A (BAF250a) whose alterations might help distinguish poorly (grade 3) differentiated endometrial carcinoma from DEAC." (PMID 29545232, 2018). "Our results suggest that Arid1a loss alone is not enough to lead to the development of endometrial cancer." (PMID 26378916, 2015).